ERLN (endoregulin)
Description:
Inhibits the activity of the calcium ATPases ATP2A2/SERCA2 and ATP2A3/SERCA3 by decreasing their apparent affinity for Ca(2+).
Synonyms: ELN; C17orf110; SMIM6
Tractability: Antibody: UniProt predicts a signal peptide or a membrane-spanning region.
Gene: Protein-coding gene on chromosome 17 (75,646,243 to 75,647,975, forward strand). Ensembl gene ENSG00000259120.
Subcellular location: Endoplasmic reticulum membrane
Subcellular location (Human Protein Atlas): Nucleoplasm
Gene Ontology:
Cellular component: endoplasmic reticulum membrane
Genetic constraint (gnomAD): Loss-of-function variants: 1 observed, 0.82 expected, observed/expected ratio (o/e) 1.22, 90% interval 0.29 to 1.91. That is too few expected variants to judge how well the gene tolerates losing a copy. Missense variants: 76 observed, 74.64 expected, observed/expected ratio (o/e) 1.02, 90% interval 0.85 to 1.23. Synonymous variants: 25 observed, 30.79 expected, observed/expected ratio (o/e) 0.81, 90% interval 0.59 to 1.13.
Homologues: Orthologues: chimpanzee SMIM6 (100% identical), rabbit ERLN (56% identical).